MTMR14 (myotubularin related protein 14)
Description:
Lipid phosphatase that specifically dephosphorylates the D-3 position of phosphatidylinositol 3-phosphate and phosphatidylinositol 3,5-bisphosphate, generating phosphatidylinositol and phosphatidylinositol 5-phosphate.
Synonyms: C3orf29; FLJ22405; FLJ90311; hJumpy; hEDTP
Tractability: PROTAC: ubiquitination databases record sites on it; its protein half-life has been measured.
Gene: Protein-coding gene on chromosome 3 (9,649,433 to 9,702,393, forward strand). Ensembl gene ENSG00000163719.
Subcellular location: Cytoplasm
Pathways (Reactome):
Autophagy: Macroautophagy
Metabolism: Synthesis of PIPs at the plasma membrane
Gene Ontology:
Molecular function: phosphatidylinositol-3,5-bisphosphate 3-phosphatase activity; phosphatidylinositol-3-phosphate phosphatase activity; protein binding; protein serine/threonine phosphatase activity
Biological process: macroautophagy; phosphatidylinositol biosynthetic process
Cellular component: cytoplasm; perinuclear region of cytoplasm; ruffle; cytosol
Genetic constraint (gnomAD): Loss-of-function variants: 45 observed, 84.73 expected, observed/expected ratio (o/e) 0.53, 90% interval 0.42 to 0.68. The upper end of that interval is the gene's LOEUF score, 0.68, which puts it in group 2 of 6, group 1 being the genes least tolerant of losing a copy. Missense variants: 779 observed, 867.14 expected, observed/expected ratio (o/e) 0.9, 90% interval 0.85 to 0.95. Synonymous variants: 366 observed, 340.14 expected, observed/expected ratio (o/e) 1.08, 90% interval 0.99 to 1.17.
Homologues: Orthologues: chimpanzee MTMR14 (99% identical), macaque MTMR14 (99% identical), pig MTMR14 (93% identical), rabbit MTMR14 (93% identical), dog MTMR14 (93% identical), guinea pig MTMR14 (92% identical), rat Mtmr14 (91% identical), mouse Mtmr14 (90% identical), tropical clawed frog mtmr14 (70% identical), zebrafish mtmr14 (64% identical), Drosophila melanogaster EDTP (36% identical).
Diseases named in the same sentence as MTMR14 in open-access papers:
MTMR14 is named in the same sentence as 23 diseases in open-access papers, as found by Europe PMC text mining. Sharing a sentence is not in itself a finding about the gene and the disease. The quoted sentences say what the papers report.
centronuclear myopathy (9 papers, 2008 to 2025). Centronuclear myopathy (CNM) is an inherited neuromuscular disorder characterized by clinical features of a congenital myopathy and centrally placed nuclei on muscle biopsy. "These include mutations in myotubularin 1 (MTM1) and myotubularin-related protein 14 (MTMR14) that are associated, respectively, with X-linked myotubular myopathy and congenital disease centronuclear myopathy." (PMID 27484057, 2016). "An inactivation mutation of MTMR14 was first identified in human centronuclear myopathy in 2006, suggesting that this gene is involved in muscle disease." (PMID 26697164, 2015). "In humans, defects in MTMR-14 function can lead to the incidence of centronuclear myopathy, which is a developmental muscle abnormality." (PMID 41226482, 2025). "Jumpy/MTMR14 PI3-phosphatase and Dynamin-2 (DNM2) GTPase, two causative genes of human centronuclear myopathy, are required for not only T-tubule maintenance but also proper progression of autophagy." (PMID 28063257, 2017). "MTMR14 is a newly identified phosphoinositide phosphatase that was first identified in human autosomal centronuclear myopathy." (PMID 26697164, 2015).
liver cancer (3 papers, 2021 to 2022). An epithelial or non-epithelial malignant neoplasm that arises from the liver. "It has also been found that MTMR14 knockdown inhibits migration and promotes apoptosis in liver cancer cells." (PMID 35035670, 2022). "Knocking out MTMR14 can induce autophagy to promote liver cancer cell apoptosis and inhibit cell migration ability." (PMID 33777735, 2021). "Knockdown of MTMR14 promoted cell apoptosis and inhibited migration in liver cancer cells." (PMID 34238288, 2021). "Furthermore, it was also reported that MTMR14 knockdown promoted apoptosis in liver cancer cells." (PMID 35035670, 2022).
Obesity (3 papers, 2015 to 2024). Accumulation of substantial excess body fat. "A series of physiological indexes demonstrated that the loss of MTMR14 induced obesity in an age-dependent manner, as reflected by body weight, energy intake and expenditure, blood biochemical indexes, and fat accumulation." (PMID 26697164, 2015). "The present study evaluated the role of MTMR14 in the development of aging-associated obesity." (PMID 26697164, 2015). "Similarly, apabetalone differentially reduced gene expression of the phagocytic macrophage receptor CD68, of the IL-10 receptor subunit IL10RB implicated in pro- and anti-inflammatory homeostasis, and of MTMR14 encoding a phosphoinositide phosphatase involved in metabolic dysregulation in obesity." (PMID 33172487, 2020). "The weight of adult MTMR14-KO mice increases more quickly than that of wild type mice, indicating that MTMR14 is involved in obesity." (PMID 38529329, 2024). "The current study included a series of experiments to delineate the potential role of MTMR14 in obesity." (PMID 26697164, 2015). "Further research demonstrated that the PI3K/AKT and ERK signaling pathways are involved in MTMR14 deletion-regulated obesity." (PMID 26697164, 2015). "Our current research suggests that MTMR14 deletion induces overweight and adult obesity accompanied by chronic inflammation in an age-dependent manner." (PMID 26697164, 2015). "We used MTMR14 KO male mice as a working model to investigate the mechanism of MTMR14 in obesity." (PMID 26697164, 2015).
cardiac hypertrophy (2 papers, 2020 to 2022). "To evaluate the link between MTMR14 and heart hypertrophy, we first tested the expression of MTMR14 in a mouse model of CH." (PMID 32080168, 2020).
muscle disorder (2 papers, 2018 to 2024). "MTMR14 plays an important role in regulating muscle performance, autophagy, and senescence in mice, whereas its deficiency induces muscle disorders." (PMID 39199880, 2024). "Our previous reports have shown that deficiency of MTMR14, a novel phosphoinositide phosphatase, induces a muscle disorder by disrupting Ca2+ homeostasis." (PMID 30412589, 2018). "First, they found that deficiency of this gene induces a muscle disorder by disrupting Ca2+ homeostasis; In MTMR14 knockout mice, spontaneous Ca2+ leakage from the sarcoplasmic reticulum occurred." (PMID 30412589, 2018).
Cerebral ischemia (1 paper, 2021). Restriction of arterial blood supply to the brain associated with insufficient oxygenation to support the metabolic requirements of the tissue. "In addition, PTEN-dependent autophagy in cerebral ischemia/reperfusion injuries has been linked to the neuroprotective activity of MTMR14." (PMID 34114972, 2021).
emphysema (1 paper, 2022). "We demonstrated that overexpression of MTMR14 reduces inflammation, apoptosis, and the progression of emphysema in vivo and in vitro." (PMID 35035670, 2022). "MTMR14 overexpression inhibited lung inflammation and reduced levels of IL-6 and KC in bronchoalveolar lavage fluid, as well as prevented emphysema and a decline in lung function." (PMID 35035670, 2022). "MTMR14 alleviates inflammation and emphysema in COPD, which depends, to a certain extent, on the regulation of mitochondrial function and mitophagy." (PMID 35035670, 2022). "Finally, in vivo studies confirmed that MTMR14 inhibited inflammation and the development of emphysema in COPD model mice." (PMID 35035670, 2022).
Hepatic steatosis (1 paper, 2015). Steatosis is a term used to denote lipid accumulation within hepatocytes. "However, the decompensation of liver occurred when hepatic steatosis was increased in adult MTMR14 KO mice." (PMID 26697164, 2015).
Infertility (1 paper, 2018). "The high expression of MTMR14 suggests that male fertility is affected by MTMR14, deficiency of which can lead to male abnormal fertility or infertility." (PMID 30412589, 2018). "This outcome further proved that MTMR14 can result in subfertility rather than infertility." (PMID 30412589, 2018).
ovarian carcinoma (1 paper, 2021). A malignant neoplasm originating from the surface ovarian epithelium. "Moreover, CXCR4, IFNG, IL24, MTMR14, and RB1 all exhibited higher expression in ovarian cancer compared to normal specimens." (PMID 33748162, 2021). "Furthermore, IFNG, IL24, MTMR14, and RB1 were highly expressed in ovarian cancer than normal tissues." (PMID 33748162, 2021). "HDAC1, PEX3, MTMR14, and RB1 had the moderate intensity and high quantity in ovarian cancer." (PMID 33748162, 2021).
sarcopenia (1 paper, 2014). Progressive decline in muscle mass due to aging which results in decreased functional capacity of muscles. "In 2010, multiple research groups identified mutations to MTMR14, one member of this gene family, in several patients with CNMs and in sarcopenia." (PMID 24600395, 2014). "Using MTMR14 specific knockout mice, a number of research groups explored the function of MTMR14 and identified MTMR14 as a contributory factor in sarcopenia." (PMID 24600395, 2014).
steatosis (1 paper, 2015). Increased lipid within the cytoplasm of cells. "The elevated MCP-1 expression level in adipose tissue and increased TNF-α, PEPCK and G6P levels in liver verified the high glyceroneogenesis and hepatic steatosis state in aged MTMR14 KO mice in our study." (PMID 26697164, 2015).
cardiovascular diseases (2 papers, 2015 to 2020). "In addition, our study contributes to a deeper understanding of the role of MTMR14 in cardiovascular diseases, and establishes a molecular link between MTMR14 and Akt in the regulation of myocardial remodeling and CH progression." (PMID 32080168, 2020). "Moreover, in our future study, MTMR14 acting as an exogenous gene can be introduced through AAV9 adeno-associated virus or adenovirus, which may have a therapeutic effect on CH as well as other cardiovascular diseases." (PMID 32080168, 2020). "MTMR14 is highly expressed in the heart, and a high-fat diet (HFD) might induce a series of severe cardiovascular diseases in MTMR14 KO mice." (PMID 26697164, 2015).
metabolic disorder (2 papers, 2015 to 2024). "There are also studies demonstrating that elder MTMR14-KO mice display more severe fatty accumulation and metabolic disorder, suggesting that MTMR14-mediated inflammation and metabolic disorder are age-dependent." (PMID 38529329, 2024). "Further analysis shows that MTMR14 deletion results in fatty accumulation, inflammation, and metabolic disorder by releasing serum cytokines, abnormal regulation of several modulatory genes and the PI3K/AKT and ERK signaling pathways." (PMID 38529329, 2024). "The reduction of adiponectin in aged MTMR14 KO mice demonstrated a severe inflammation and metabolic disorder during aging." (PMID 26697164, 2015). "Generally, MTMR14 deficiency promoted the phosphorylation of AKT and ERK in aged KO mice, and evoked a crosstalk between adipose tissue and inflammatory system, which created inflammation and metabolic disorders." (PMID 26697164, 2015). "Taken together, our findings suggest that MTMR14 deficiency evokes severe inflammation via the up-regulation of TNF-α and IL-6, and the metabolic disorders may depend on elevated leptin and decreased adiponectin." (PMID 26697164, 2015).
cardiac diseases (1 paper, 2020). "Therefore, the use of strategies designed to target MTMR14 is of interest for the metabolic and contractile remodeling in cardiac diseases." (PMID 32080168, 2020). "Further study on the correlations between MTMR14 and CH may provide guidance for the treatment of certain types of cardiac disease." (PMID 32080168, 2020).
neurodegenerative disease (1 paper, 2024). A disorder of the central nervous system characterized by gradual and progressive loss of neural tissue and neurologic function. "MTMR14, a gene that encodes a myotubularin‐related protein, has been reported to inhibit deleterious overactivation of autophagy, which is frequently associated with various neurodegenerative diseases, including PD." (PMID 39578713, 2024).
MTMR14 also shares sentences with these, for which no sentence is quoted: X-linked myotubular myopathy (2 papers); cancer (1); chronic obstructive pulmonary disease (1); congenital myopathies (1); ischemia (1); prostate carcinoma (1); prostate tumor (1).